TPBGL (trophoblast glycoprotein like)
Tractability: Antibody: UniProt predicts a signal peptide or a membrane-spanning region; its Gene Ontology location is reachable by antibodies, with medium confidence.
Gene: Protein-coding gene on chromosome 11 (75,240,774 to 75,243,704, forward strand). Ensembl gene ENSG00000261594.
Subcellular location: Membrane
Gene Ontology:
Biological process: negative regulation of canonical Wnt signaling pathway
Cellular component: plasma membrane; membrane
Genetic constraint (gnomAD): Missense variants: 685 observed, 357.97 expected, observed/expected ratio (o/e) 1.91, 90% interval 1.79 to 1.99. Synonymous variants: 380 observed, 189.8 expected, observed/expected ratio (o/e) 2.
Homologues: Orthologues: chimpanzee TPBGL (99% identical), macaque TPBGL (98% identical), guinea pig TPBGL (87% identical), rat Tpbgl (87% identical), mouse Tpbgl (86% identical), rabbit TPBGL (85% identical). Paralogues in human: LRFN3 (24% identical), LRFN1 (24% identical), LRRN2 (23% identical), LRRC55 (23% identical), TLR9 (23% identical), LRFN2 (23% identical), LRFN4 (22% identical), SLIT3 (22% identical), LRFN5 (21% identical), SLIT1 (21% identical), GP5 (20% identical), SLIT2 (20% identical), and 13 more.